CNR1 (cannabinoid receptor 1)
Diseases named in the same sentence as CNR1 in open-access papers (continued):
Sharing a sentence is not in itself a finding about the gene and the disease.
memory impairment (25 papers, 2015 to 2025). "LXA4 exerts a protective effect against memory impairment in animals through the activation of cannabinoid receptor 1 (CB1)." (PMID 36114383, 2022). "THC can produce brief psychotic symptoms through dopaminergic dysfunction and memory impairment through stimulation of cannabinoid receptor-1 (CB1R)." (PMID 34925083, 2021). "In addition, APP/PS1/CB1R–/– mice (APP/PS1 mice with additional CNR1 knockout) developed accelerated memory impairments in the two-object recognition test." (PMID 36117622, 2022).
migraine (24 papers, 2011 to 2026). "Variants in the cnr1 gene (encodes for the CB1 receptor) resulting in decreased expression of CB1 associated with migraine and trigeminovascular activation." (PMID 28861505, 2017). "Results from a genetic study demonstrated a significant haplotypic effect of CNR1 (the gene of CBR-1) on headaches with migraine symptoms (e.g., nausea, photophobia, disability) only when using extreme trait combinations (0 symptoms versus 3 symptoms)." (PMID 36835524, 2023). "In addition, in a study of actual clinical cases, rare heterozygous coding variants in CNR1, which encodes CB1R, were significantly associated with pain sensitivity, particularly in patients with migraine." (PMID 33014123, 2020).
diabetic nephropathy (23 papers, 2019 to 2025). "There was a predictable association between CNR1 polymorphisms (rs1776966256 and rs1243008337) and susceptibility to diabetic nephropathy in the Iraqi population." (PMID 38406790, 2023). "It is unclear how the CNR1 gene polymorphism affects the transmission of vulnerability to diabetic nephropathy." (PMID 38406790, 2023). "In the current study, the genetic relationship between the CNR1 rs1776966256 and rs1243008337 polymorphisms and susceptibility to diabetic nephropathy in the Iraqi population was investigated." (PMID 38406790, 2023). "However, their more recent study used a Cnr1 deletion model, allowing them to explore the role of CB1 in the development of diabetic nephropathy in vivo." (PMID 37408253, 2023).
Hypertension (23 papers, 2011 to 2024). The presence of chronic increased pressure in the systemic arterial system. "Cnr1 and Cnr2 expression was upregulated in both types of arteries and hypertension models, in comparison to their respective controls." (PMID 34832902, 2021).
liver diseases (21 papers, 2010 to 2025). "In monogastric animals, upregulation of CNR1 in the liver was reported to be associated with liver diseases such as hepatitis, non-alcoholic fatty liver, and immune dysfunction; none of those were observed in our experiments with dairy cows and lambs." (PMID 39062742, 2024). "Increased cannabinoid 1 receptor (CNR1) expression is found in liver diseases such as NAFLD." (PMID 39858445, 2025). "Within it, two specific G-protein receptors have been identified that may play a role in liver disease, namely, cannabinoid receptor 1 (CB1) and cannabinoid receptor 2 (CB2)." (PMID 34298967, 2021).
atherosclerosis (20 papers, 2015 to 2026). A disease characterized by the build-up of fatty material and calcium deposition in the arterial wall resulting in partial or complete occlusion of the arterial lumen. "Our previous work identified genistein, a soy isoflavone, as a cannabinoid receptor 1 (CB1) antagonist capable of suppressing CB1-mediated vascular inflammation and atherosclerosis." (PMID 41559687, 2026).
cannabis dependence (20 papers, 2012 to 2025). Physical and psychological dependence on the drug cannabis. "Variants in the CNR1 gene (encoding CB1 receptors) have been linked to differences in cannabis dependence and response." (PMID 40652292, 2025). "Some other CNR1 haplotypes (rs6454674, rs806377, rs1049353) were associated with cannabis dependence." (PMID 37185752, 2023). "SNP ID at the rs806368, C allele has been associated with an increased risk of cannabis dependence and with a lower expression of CNR1 in the brain." (PMID 37185752, 2023). "A microsatellite polymorphism of CNR1 has also been positively associated with intravenous drug use and cocaine, amphetamine, and cannabis dependence." (PMID 35629112, 2022). "They found that SNP rs806380, located in intron 2 of the CNR1 gene, was significantly associated with developing cannabis dependence symptoms, with the G allele having a protective effect." (PMID 35563156, 2022). "The rs806380 SNP in intron 2 of CNR1 has been associated with cannabis dependence." (PMID 35629112, 2022). "The rs806380 SNP in intron 2 of CNR1 is associated with cannabis dependence." (PMID 36579510, 2022). "While some studies emphasize a strong link with cannabis-dependence symptoms, others have not found a significant association between CNR1 rs1049353 and substance abuse or cannabis dependence." (PMID 37509416, 2023). "More importantly, CNR1 mRNA levels correlate with a lower score on the Satisfaction With Life Scale (SWLS) and with craving and cannabis dependence, results in agreement with previous animal studies showing a relationship between craving and CNR1 gene expression." (PMID 35327588, 2022).
Nephropathy (20 papers, 2015 to 2025). A nonspecific term referring to disease or damage of the kidneys. "Our work thus further elevated our understanding of the role of Cnr1 in renal cilia, especially MCC development, further elucidating the connection between Cnr1 and the endocannabinoid signaling pathway as a whole to kidney diseases." (PMID 40558673, 2025). "Our findings indicate that cnr1 has a critical role in controlling renal MCC development both via cAMP signaling and an independent pathway, further revealing implications for ciliopathies and renal diseases." (PMID 40558673, 2025). "Previous reports have shown the presence of the key endocannabinoid receptor Cannabinoid receptor 1 (CB1 or Cnr1) in multiciliated (MCC) tissues and its upregulation in kidney diseases, yet the relationship between Cnr1 and renal MCC development is unknown." (PMID 40558673, 2025). "Recent studies have suggested that targeting the endocannabinoid system, particularly the cannabinoid receptor 1 (CB1) and cannabinoid receptor 2 (CB2), may have therapeutic potential in various kidney diseases." (PMID 38360685, 2024).
Huntington disease (19 papers, 2013 to 2025). Huntington disease (HD) is a rare neurodegenerative disorder of the central nervous system characterized by unwanted choreatic movements, behavioral and psychiatric disturbances and dementia. "Moreover, M6 was retrospectively mapped to InN3, and molecules enriched in the path, such as Cnr1, were found to be associated with the age of Huntington’s disease onset." (PMID 39635132, 2024). "Furthermore, we found that some DORCs, such as CNR1, HOMER1, ADORA2A, and DRD2, have been reported to be downregulated in patients with Huntington's disease in the striatum." (PMID 38091510, 2022).
melanoma (19 papers, 2012 to 2025). A malignant, usually aggressive tumor composed of atypical, neoplastic melanocytes. "Since melanoma is a genetically highly heterogenous disease, we were interested if CNR1, PPARα and TRPV1 are frequently mutated and therefore not accessible for inhibitory therapy." (PMID 37237519, 2023). "Cnr1/2−/− mice were crossed into the Hgf-Cdk4R24C melanoma mouse model to generate mice with a dark skin phenotype which develop CB1 and CB2 receptor-deficient melanomas." (PMID 27774065, 2016).
alcohol dependence (17 papers, 2011 to 2026). Physical and psychological dependence on alcohol. "The GMDR analysis suggests that a certain combination of SNPs along the CNR1-DAGLA-MGLL genes protect against or pose a risk for alcoholism, by presumably modulating DAGLA and or MGLL expression and subsequently 2-AG levels." (PMID 33959052, 2021). "The single nucleotide polymorphism (SNP) rs1049353 in the CNR1 gene has been associated with severe alcoholism (minor A allele), heroin addiction (major G allele), and impulsivity." (PMID 33959052, 2021). "A recent meta-analysis of genetic and genome-wide association studies exploring the correlations between the CNR1 SNPs, and the risk of alcohol dependence found that three CNR1 SNPs (rs1535255, rs2023239, and rs806379) were associated with the development of alcohol dependence." (PMID 35563156, 2022). "Previously, CNR1 rs806368 was reported to be associated with cannabis, cocaine, nicotine dependence, and in interaction with rs6454674 is known to increase the risk for drug and alcohol dependence." (PMID 34566715, 2021). "This procedure reduced CNR1 gene expression, causing a subsequent reduction in alcohol intake in the two-bottle choice paradigm, supporting the involvement of ECS in alcohol dependence." (PMID 35327588, 2022). "Two polymorphisms of CNR1, rs6454674 (SNP3) and rs806368 (SNP8), have been strongly associated with both alcohol dependence and drug dependence." (PMID 35327588, 2022).
hepatocellular carcinoma (17 papers, 2010 to 2025). A malignant tumor that arises from hepatocytes. "It has been recently shown through in vitro and animal studies that the cannabinoid receptor 1 (CB-1) contributes to liver injury, inflammation and may be involved in the initiation of hepatocellular carcinoma through endocannabinoid system activation." (PMID 28705172, 2017).
substance abuse (16 papers, 2011 to 2025). The use of a drug for a reason other than which it was intended or in a manner or in quantities other than directed. "In candidate gene studies, SNPs in CNR1 (rs2023239) and FAAH (rs324420) have been associated with substance abuse and functional changes in cannabinoid regulation." (PMID 40442827, 2025). "It has been reported that genomic variations in the human CB1 receptor gene (Cnr1) appear to be involved in the vulnerability towards substance abuse and addictive behaviors." (PMID 22347447, 2012).
mood disorder (15 papers, 2016 to 2025). A cognitive disorder a disturbance in which the person's mood is hypothesized to be the main underlying feature. "Comparisons of affective disorder patients with and without THC or ethanol exposure revealed upregulated expression of the CNR1 gene in the patients with mood disorders." (PMID 32433545, 2020). "Third, several genetic variants of CNR1, the CB1-coding gene, located on chromosome 6q14–15 (NC_000006.12), have been associated with either addictive or mood disorders in case–control studies, highlighting again the potential therapeutic properties of the pharmacological modulation of this target." (PMID 33692705, 2021).
mantle cell lymphoma (13 papers, 2013 to 2025). Mantle cell lymphoma is a rare form of malignant non-Hodgkin lymphoma affecting B lymphocytes in the lymph nodes in a region called the ``mantle zone''. "A previous study showed that CNR1 was over expressed in Mantle Cell Lymphoma (MCL) B-cells compared to non-malignant B-cells and that targeting the endocannabinoid receptors was suggested in the treatment of MCL." (PMID 33921415, 2021).
Cirrhosis (12 papers, 2010 to 2022). A chronic disorder of the liver in which liver tissue becomes scarred and is partially replaced by regenerative nodules and fibrotic tissue resulting in loss of liver function. "Cannabinoid receptor 1 (CB1R) is a G-protein coupled receptor, whose expression is unregulated in the liver with viral hepatitis, alcoholic and nonalcoholic fatty liver disease, and cirrhosis." (PMID 36293428, 2022). "The results revealed the significant diagnostic values of PF4 and PPBP in cirrhotic HCC, and CCL19, CCL25 in non-cirrhotic HCC, while no significant diagnostic values of CNR1 in HCC with or without cirrhosis were found." (PMID 31346321, 2019). "Besides, CNR1 expression was upregulated in HCC with or without cirrhosis than that in compared normal tissues both in TCGA and qRT-PCR results." (PMID 31346321, 2019).
endometriosis (12 papers, 2017 to 2025). The growth of functional endometrial tissue in anatomic sites outside the uterine body. "Transcriptomic profiling of endometriosis-like lesions from canonical receptors (CNR1 and CNR2) knockout mice reveals extensive differential gene expression and altered pathways." (PMID 39120997, 2024). "Women with endometriosis exhibited decreased expression of cannabinoid receptor 1 (CB1R) in lesions compared to controls, as well as increased levels of the endogenous ligands of CB1R and CB2R, Arachidonoylethanolamine (AEA), and 2-Arachnidonoyl glycerol (2-AG)." (PMID 39162801, 2024).
neuropathy (12 papers, 2011 to 2024). A disorder affecting the nervous system that manifests with pain, tingling, numbness, and/or muscle weakness. "We analyzed genes known to be targeted by cannabigerol and other cannabinoids, including Cnr1, Cnr2, Gpr55, Faah, Mgll, Adra2a-c, Pparg, or to have been previously published as volatile in a cisplatin-induced neuropathy setting in DRG, including Drd2, Gfap, and Oprm1." (PMID 37895913, 2023). "Administration of cannabinoid receptor 1 (CB1R) and 2 (CB2R) agonists does reduce pain in many animal pain models and may be a target for treatment of neuropathy." (PMID 30158958, 2018).
nicotine dependence (11 papers, 2011 to 2025). Physical and psychological dependence on nicotine. "We have reported that the cannabinoid receptor 1 target is associated with tobacco smoking and nicotine dependence." (PMID 22205969, 2011). "Distinct CNR1 gene allelic variants have been studied in patients with nicotine dependence." (PMID 35327588, 2022). "Some polymorphisms of the CNR1 gene have been suggested to be associated with nicotine dependence, and, interestingly, the rs806379 SNP appears to be a protective factor, since it has been related to an attenuated cognitive disruption during nicotine withdrawal." (PMID 35327588, 2022).
renal fibrosis (11 papers, 2016 to 2025). A final common manifestation of a wide variety of chronic kidney diseases characterized by glomerulosclerosis and tubulointerstitial fibrosis. "Regarding the relationship between CB1 and renal fibrosis, it was reported that, in a renal fibrosis model induced by unilateral ureteral obstruction (UUO), the fibrotic area was reduced to about 2/3 that in wild-type mice by CB1 (CNR1) gene knockout." (PMID 27936102, 2016).
autism (10 papers, 2011 to 2025). Persistent deficits in social interaction and communication and interaction as well as a markedly restricted repertoire of activity and interest as well as repetitive patterns of behavior. "Apart from protein expression, CNR1 was also reported to be significantly downregulated in postmortem brains of individuals with autism." (PMID 33080916, 2020).
ischemia (10 papers, 2015 to 2023). A hypoperfusion of the BLOOD through an organ or tissue caused by a PATHOLOGIC CONSTRICTION or obstruction of its BLOOD VESSELS, or an absence of BLOOD CIRCULATION. "Cannabinoid receptor 1 (CB1) is expressed in neurons and immune cells, and its activation has been shown to produce neuroprotective effects in ischemia." (PMID 37869749, 2023).
substance dependence (10 papers, 2018 to 2024). The psychological or physiological need to take a substance in order to experience its effects or to avoid the effects of its absence. "Although previously linked to substance dependence, the cannabinoid receptor 1 (CB1, with a direct role in the dopaminergic reward pathway) has been associated with cocaine addiction as well, being relevant for relapse into cocaine-seeking behavior." (PMID 37446631, 2023). "Here we have found that the minor allele of rs806368, a risk allele for substance dependence, is associated with lower expression of a novel CNR1 transcript in DLPFC." (PMID 32433545, 2020). "Genetic polymorphism of CNR1 gene is known to be associated with substance dependence in Caucasians." (PMID 29593587, 2018).
anxiety disorder (9 papers, 2017 to 2023). A category of psychiatric disorders which are characterized by anxious feelings or fear often accompanied by physical symptoms associated with anxiety. "Genetic studies pointed out interesting results regarding the involvement of polymorphisms or epigenetic modifications of CNR1 as susceptibility/risk biomarkers to develop anxiety disorders." (PMID 32395111, 2020). "Single nucleotide polymorphisms (SNPs) in the CB1 receptor gene (CNR1) have been linked to mood and anxiety disorders, such as PTSD and major depression." (PMID 30239920, 2018). "In the current study, we tested the association between polymorphisms of the CNR1, CNR2, and FAAH genes and response to CBT in children and adolescents with an anxiety disorder diagnosis." (PMID 27346075, 2017). "Given the potential role of the ECB system in fear extinction and the maintenance of extinction memories, this study investigated whether genetic variation in the CNR1, CNR2, and FAAH genes was associated with response to CBT in children and adolescents with an anxiety disorder." (PMID 27346075, 2017). "We investigated the relationship between variation in the CNR1, CNR2, and FAAH genes and change in primary anxiety disorder severity between pre‐ and post‐treatment and during the follow‐up period in the full sample and a subset with fear‐based anxiety disorder diagnoses." (PMID 27346075, 2017).
bipolar disorder (9 papers, 2017 to 2023). A disorder of the brain that causes unusual shifts in mood, energy, activity levels and the ability to carry out day-to-day tasks. "The CNR1 gene is located at the chromosome 6q14-15, a locus possible related to susceptibility for bipolar affective disorder." (PMID 29311804, 2017). "Moreover, a direct association between CNR1, CNR2 and FAAH polymorphisms and bipolar disorder susceptibility has also been described." (PMID 29311804, 2017).
fibrosis (9 papers, 2010 to 2022). the formation of excess fibrous connective tissue in an organ or tissue in a reparative or reactive process. "In a CCl4-fibrosis murine model, BMDMs were found to be recruited via cannabinoid receptor 1 (CB1), which has also been demonstrated to be involved in the expression of pro-fibrotic and pro-inflammatory cytokines." (PMID 34944564, 2021).
Anorexia (8 papers, 2017 to 2025). Lack of desire to eat (loss of appetite). "In an activity-based anorexia rat model, Cnr1 gene expression was associated with significant increases in DNA methylation at the Cnr1 gene promoter in the HTM and nucleus accumbens (NAc) brain regions." (PMID 36358910, 2022).
COVID-19 (8 papers, 2020 to 2026). A disease caused by infection with severe acute respiratory syndrome coronavirus 2. "Lastly, gene expression of CB2 cannabinoid receptors CNR2 was raised in GCs-treated COVID-19 individuals compared to control, and there was a trend toward increased expression of CNR1." (PMID 36851787, 2023).
cocaine dependence (7 papers, 2013 to 2023). A psychologically and socially impaired state, with or without physiological changes, that develops as a result of using cocaine and which leads to compulsive behaviors to acquire the substance. "Therefore, all these studies confirm the association between CNR1 variants and cocaine dependence in different ethnicities." (PMID 35327588, 2022). "Similarly, a study from Ballon and colleagues shows that detection of this CNR1 polymorphism in a sample of 142 African-Caribbean individuals predisposed them to cocaine addiction." (PMID 24069004, 2013). "Two independent CNR1 variants, the G allele genotypes of rs6454674 (SNP3^G+) and the T/T genotype of rs806368 (SNP8^T/T), have significant interaction effects on the risk of cocaine dependence in European Americans (EA), as well as in African Americans (AA) with these genotypes." (PMID 35327588, 2022).